CD47 (CD47 molecule)
Diseases named in the same sentence as CD47 in open-access papers (continued):
Sharing a sentence is not in itself a finding about the gene and the disease.
cancer (continued). "Cancer cells can escape macrophage-mediated phagocytosis through expression of CD47, which interacts with SIRPα on the surface of macrophages to trigger the “don’t eat me” signal." (PMID 35229723, 2022). "The relevance of m7G-cap-dependent RNA trafficking to the physiological functions of CD47 in cardiovascular disease, aging, cancer, and infection remain to be investigated." (PMID 34841476, 2022). "Immunotherapeutic approaches that block the CD47‐SIRPα signalling axis have yielded promising preclinical activity, with prominent induction of phagocytosis in various cancer types." (PMID 35908284, 2022). "To understand the relationship between CD47 and various cancers, we explored the RNA expression level of CD47 in different cancers and matched normal tissues." (PMID 35697717, 2022). "CD47 performs a vital function in cancer therapy by binding to different SIRPα, thrombospondin 1, and integrin." (PMID 35697717, 2022). "CD47 was initially discovered in ovarian cancer cells but expressed in all cells and overexpressed in cancer cells as a “self-marker,” delivering an inhibitory “don’t eat me” signal by engaging in SIRPα, thereby avoiding phagocytosis by macrophages." (PMID 36497444, 2022). "In mixed cultures with CD47-expressing cancer cells, DSP107 augmented T cell cytotoxicity in vitro in an effector-to-target ratio-dependent manner." (PMID 35287686, 2022). "Neutralising anti-CD47 mAbs have recently begun early phase clinical investigation across different cancer types." (PMID 35020853, 2022). "The cluster of differentiation 47 (CD47) protein, expressed on both healthy and cancer cells, plays a pivotal role in this balance by delivering a “do not eat me signal” upon binding to the signal-regulatory protein alpha (SIRPα) receptor on myeloid cells." (PMID 36080360, 2022). "TGCT nanocascaded enzymes were created through the reaction of GOX and CPO onto Ti3C2 nanosheets with TPZ drug loading and the biomimetic alteration of CD47-overexpressed cancer cell membrane offer a bionic cascaded-enzyme nanoreactor (as meTGCT)." (PMID 36296126, 2022). "In phase I and II clinical trials, anti-CD47 antibody or SIRPαFc treatment has shown safety, tolerability, and efficacy in advanced colorectal cancer, non-Hodgkin’s lymphoma for cancer immunotherapy." (PMID 35646915, 2022). "Cancer cells can adopt mechanisms to evade immune surveillance; an example is to express high levels of the transmembrane protein CD47, which represents the classic signal “don’t eat me”, inducing an anti-phagocytic response." (PMID 35711414, 2022). "HIF-1α transcriptionally upregulates the expression of CD47, which helps to escape the phagocytosis of macrophages and maintain the stem phenotype of breast CSCs (cancer stem cells)." (PMID 36139678, 2022). "Many types of cancer overexpress CD47 to escape innate immunity, with the expression of CD47 often correlating with poor patient survival and poor response to standard therapy." (PMID 35287686, 2022). "As such, CD47 has recently be regarded as one of novel innate checkpoint receptor targets for cancer immunotherapy." (PMID 36081498, 2022). "By binding CD47 on cancer cells, DSP107 blocks the CD47/SIRPα cross talk, thereby inducing phagocytosis of cancer cells." (PMID 35978372, 2022). "Much progress including ongoing clinical trials has been made in targeting CD47 for cancer immunotherapy in solid tumors and hematological malignancies." (PMID 36494694, 2022). "The CD47 CAR facilitates binding to CD47 positive cancer cells, increasing the chances of TAG72 positive cancer cells’ elimination via STn CAR." (PMID 35158915, 2022). "CD47/SIRPα axis is recognized as an innate immune checkpoint and emerging clinical data validate the interest of interrupting this pathway in cancer, particularly in hematological malignancies." (PMID 35538512, 2022).
cancer (continued). "CD47 is a key immune checkpoint which is highly expressed on a variety of cancer cells, making tumor cell resistant to host immune surveillance." (PMID 35372077, 2022). "DSP107 assembles into a natural homotrimer due to the 4-1BBL trimerization domain and, upon binding to CD47 on cancer cells, breaks the CD47:SIRPα interaction." (PMID 35287686, 2022). "Herein, modulation of the TAM-dying cancer cell interface by targeting phagocytic pathways (e.g., CD47-SIRP1α, CAR-macrophages) is poised to be the next big breakthrough in immuno-oncology, contingent on successful results in ongoing clinical trials." (PMID 36497148, 2022). "CD47 is the best studied in antitumor treatment, and anti-CD47 antibody-based therapies targeting the CD47-SIRPα axis enhance the phagocytosis of cancer cells by macrophages." (PMID 35222345, 2022). "Originally, the antitumor activity of CD47/SIRPα axis inhibitors has been attributed to enhanced direct killing of cancer cells, principally by macrophage-mediated ADCP." (PMID 35538512, 2022). "Doxorubicin was shown to upregulate CD47 and, while combined with ant-CD47 mAbs, had reduced cardiotoxicity and improved anti-cancer effect." (PMID 36429020, 2022). "In order to confirm that the fluorescence detected on the cancer is the result of specific binding to CD47, we first incubated one sample with isotype immunoglobulin G (IgG)-Alexa Fluor 790 as a negative control." (PMID 35295998, 2022). "CD47 is a “don’t eat me” immune checkpoint signaling receptor, which is constitutively expressed by normal cells and overexpressed on cancer cells, while CD47 binds signal regulatory protein α, expressed by TAMs, DCs and neutrophils." (PMID 35664746, 2022). "TTI-621 is a fully human recombinant protein that blocks the CD47–SIRPα axis and improves the killing of cancer cells." (PMID 35158779, 2022). "CD47 upregulation was detected in various cancer cells, serving a powerful mechanism of evading macrophage killing." (PMID 36454036, 2022). "These include approaches that aim at inhibiting the CD47 “don’t-eat-me” signal produced by cancer cells and/or the SIRPα receptor for CD47 on macrophages, as well as stimulation of Toll-like receptor (TLR) signaling with TLR agonists." (PMID 36240276, 2022). "Recent studies have reported the presence of particular membrane proteins, for example, CD47, and EpCAM on the cancer cell membranes that regulate immune tolerance and the cell adhesion ability of cancer cells to avoid macrophage uptake." (PMID 36365249, 2022). "CD47 is expressed on cancer cells and inhibits the phagocytosis via interaction with SIRP-α on macrophages." (PMID 35328721, 2022). "In sum, all the data in the current study suggested the CD47 as an effective prognostic biomarker in various types of human cancers." (PMID 35697717, 2022). "Accumulating studies reveal that cell surface expression of CD47 is a common mechanism by which cancer cells protect themselves from phagocytosis." (PMID 35295998, 2022). "Conversely, CD47 overexpression decreased the sensitivity of cancer cells to phagocytosis, leading to reversal of the increased phagocytosis of the SIRPγ-knockdown cancer cells by macrophages." (PMID 35229723, 2022). "All tissue specimens were used for immunohistochemistry to compare CD47 protein expression in normal and cancer tissue." (PMID 35295998, 2022). "Taken together, targeting the innate immune checkpoint CD47-SIRPα has great potential to potentiate antibody therapy in cancer." (PMID 35884427, 2022). "Several factors can contribute to cancer immune escape, including the “don’t eat me” signal CD47, which is upregulated in all human patient cancer cells that have been tested." (PMID 36362004, 2022). "Magrolimab as an anti-CD47 antibody interferes with this escape mechanism, which results in natural immune activation against cancer cells." (PMID 35328721, 2022). "In recent years, much progress has been made in targeting CD47 for cancer immunotherapy in solid tumors." (PMID 36230638, 2022).
cancer (continued). "CD47 upregulation was found in many types of cancer cells, in which CD47 provides an important mechanism to evade macrophage killing." (PMID 36454036, 2022). "DSP107 effectively blocked the CD47/SIRPα checkpoint and potentiated phagocytic uptake of cancer cells by macrophages and PMNs in vitro." (PMID 35287686, 2022). "Signal regulatory protein alpha (SIRPα) on TAMs interacts with CD47, a “don't eat me” signal on cancer cells, preventing the phagocytosis of macrophages for cancer cells." (PMID 35585567, 2022). "There are two emerging CD47-targeting strategies for cancer therapy, including interrupting the binding of CD47/SIRPα and downregulating CD47 expression at the transcriptional, translational, and post-translational levels." (PMID 36274066, 2022). "Most cancer cells express CD47 on the surface; CD47 is known to bind to signal regulatory protein α (SIRPα)." (PMID 35989351, 2022). "It has an extracellular immunoglobulin (Ig)-like domain to bind its ligand CD47 which is often over-expressed on cancer cells." (PMID 36465350, 2022). "Researches have shown that EMT-activated cancer cells can take advantage of immune-checkpoint molecules (ICMs), such as CD47, to achieve immune escape by delivering a “don’t eat me” signal to macrophages in breast cancer." (PMID 35152264, 2022). "In the tumor microenvironment, cancer cells trick macrophages by expressing CD47, a “don’t eat me” signal, on their cellular surface and protect them from phagocytosis via binding to signal regulatory protein alpha (SIRPα) receptor on macrophages." (PMID 35216342, 2022). "CD47 acts like an antiphagocytic signal for phagocytic cells; blockade of CD47 with mAbs induce therefore macrophage phagocytosis of cancer cells." (PMID 35078492, 2022). "Mounting evidence demonstrates that inhibition of the SIRPa–CD47 innate immune checkpoint is an effective and novel way for cancer therapy." (PMID 35697717, 2022). "While monotherapy with the CD47 blockade shows efficacy in several syngeneic mouse models of cancer, it proved ineffective in clinical trials so far, except for rare cutaneous and peripheral lymphomas." (PMID 35565443, 2022). "The CD47-SIRPα interaction generates a “don’t eat me” signal, protecting cancer cells from macrophage mediated phagocytosis." (PMID 36428745, 2022). "Treatment with DSP107 alone and in combination with rituximab triggered significant pro-phagocytic activity against DLBCL cancer lines in vitro, equal to that of both CD47 mAb and SIRPα:Fc." (PMID 36429020, 2022). "Our scRNA-seq profiling together with the mining data showed that CD36 was mainly expressed by monocytes/macrophages while CD47 was broadly expressed particularly by cancer cells." (PMID 35547750, 2022). "Further, macrophage-mediated phagocytosis is a slow process that not only takes days to complete but is also inhibited by IL-10 and CD47 and PD-L1, two immune checkpoints on cancer cells." (PMID 35856032, 2022). "Based on these observations, CD47 has become a prominent target in the field of cancer immunotherapy." (PMID 35664753, 2022). "CD47 blockades have shown initial success in early- phase clinical trials for many human cancers, either alone or in combination with other agents." (PMID 36081498, 2022). "A preclinical study demonstrated that the downregulation of CD47 inhibits the growth and metastasis of human cancer cells." (PMID 36291980, 2022). "Taken together, these results suggest that anti-CD47 antibodies enhance phagocytosis in combination with mAbs in a variety of cancer models." (PMID 36970051, 2022). "Research on tri- or even tetra-specific antibodies has provided a conceptual breakthrough for a new cancer therapy, and studies of CD47/SIRPα-targeted tri- or tetra-specific antibodies for hematological malignancies are additionally required." (PMID 35978372, 2022).
cancer (continued). "At the post-translational modification level, QPCTL (glutaminyl-peptide cyclo-transferase-like protein) disrupts CD47 pyroglutamate formation and is regarded a novel target to augment antibody therapy of cancer." (PMID 36081498, 2022). "Beyond that, targeting the checkpoint molecule CD47 led to similar results in a mouse model of PDAC, as CD47 on cancer cells inhibits macrophage phagocytosis, causing M2 macrophage polarization." (PMID 35418973, 2022). "Knockout of SLAMF7 in mice remarkably inhibits macrophage-mediated phagocytosis potentiated by CD47 blockade in many B cell- and myeloid cell-derived cancer cell lines." (PMID 35978372, 2022). "Adopting a similar behavior, cancer cells overexpress CD47 to escape M1 macrophage innate immune response by binding to their SIRPα ligand." (PMID 35406573, 2022). "Together, these results suggest that the 7DC-VCMMAE ADCs have an excellently targeted therapeutic effect, particularly in cancer cells that express high levels of surface CD47 antigen." (PMID 35646646, 2022). "For instance, CD47 is known to orchestrate a protective mechanism by which both (cancer) cells and EVs evade phagocytosis as it interacts with its receptor signal regulatory protein alpha (SIRPα) present on immune cells to trigger a “do not eat me” signal." (PMID 35214000, 2022). "Cancer cells can exploit the same pathway by overexpressing CD47 to mask their alien nature against macrophages." (PMID 35406573, 2022). "Preclinical studies pointed out that LILRB1 is highly expressed by TAMs and is responsible for the resistance of cancer cells expressing the common MHC-I component β2M to anti-CD47-induced phagocytosis." (PMID 35158779, 2022). "CD47 expressed on cancer cells interacts with its ligand signal regulatory protein alpha (SIRPα) on macrophages." (PMID 36428745, 2022). "Utilizing anti-CD47 antibodies open up exciting avenues in cancer, but there are still unsolved questions in this field." (PMID 36081498, 2022). "Many cancers have evolved various mechanisms to evade immunological surveillance, such as the inhibitory immune checkpoint of the CD47-SIRPα signaling pathway." (PMID 35557862, 2022). "SIRPα is established as a myeloid inhibitory immunoreceptor, which can interact with CD47 on cancer cells and send ‘don't eat me’ signal to phagocytes." (PMID 35256517, 2022). "CD47 is overexpressed in a large number of cancers and is considered a target for cancer immunotherapy." (PMID 36018888, 2022). "The theoretical basis for CD47 functioning as a promising checkpoint in cancer therapy is due to its pivotal role in balancing both inhibitory and stimulating activities of myeloid cells." (PMID 36081498, 2022). "The expression of CD47 in cancer cells enables cancer cells to initiate a “don’t eat me” signal for their escape from phagocytosis by macrophages." (PMID 35229723, 2022). "An altered ratio of expression of pro‐phagocytic CALR and anti‐phagocytic CD47 mediates evasion from immunosurveillance and is the basis for CD47‐targeting molecules as novel anti‐cancer therapies." (PMID 34618358, 2022). "The induced CD47 expression has been reported in various cancers such as ovarian carcinoma, murine myeloid leukaemia, and leukemic stem cells." (PMID 35879772, 2022). "Collagens, MIF, MDK, APP, and laminin were detected as the most significant signaling, and the top ligand-receptor interactions THBS2/THBS3 (CAFs)—CD47 (cancer cells), MDK (CAFs)—NCL/SDC2/SDC4 (cancer cells) as potential therapeutic targets." (PMID 36352420, 2022). "CD47 forms a signaling complex with SIRPα expressed on phagocytes and other immune cells, which enables cancer cells to escape macrophage-mediated phagocytosis." (PMID 36226050, 2022). "Overexpressed CD47 interacts with SIRPα on myeloid cells to help multiple malignant tumors escape immunosurveillance." (PMID 35860564, 2022).
cancer (continued). "CD47-SIRPα interaction acts as a “don’t eat me” signal and is exploited by cancer to downregulate innate and adaptive immune surveillance." (PMID 36439116, 2022). "Kaplan Meier analysis and forest plot were performed to compare the effects of high and low expression of CD47 on overall survival in different cancers." (PMID 35697717, 2022). "Given the central role of the CD47-SIRPα pathway in both innate and adaptive immunity against cancer, several agents that block this interaction have entered the clinical space, with numerous others in development." (PMID 36439116, 2022). "In other words, blockade of CD47-SIRPα signaling can promote macrophages to directly “eat” cancer cells." (PMID 35216342, 2022). "Because the effect of CD47 antagonists for cancer treatment requires blocking CD47 and SIRPα interaction, we examined CD47 expression on selected cells." (PMID 33629544, 2021). "CD47 is only one of many immune checkpoints overexpressed on the surface of cancer cells; others include Galectin-9 and programmed cell death ligand 1 (PD-L1)." (PMID 33540720, 2021). "In this review, we discussed the regulatory mechanism of CD47-mediated cancer immune escape and immunotherapy." (PMID 34512146, 2021). "As crucial innate and adaptive immune checkpoints on cancer cells, CD47 and PD-L1 coordinate to inhibit immune sensing." (PMID 34305918, 2021). "There are currently four bsAbs constructs targeting CD47 for the treatment of patients with various kinds of cancers, which are undergoing assessed in the clinics at present." (PMID 34305918, 2021). "Immunofluorescence staining of spheroid sections revealed that following NTP treatment, spheroids of both cancer types showed modulation of CD47 compared to untreated." (PMID 33540720, 2021). "CD47 is abundantly overexpressed on several types of cancer cells (especially cancer stem cells) representing a potent strategy for immune evasion." (PMID 34831455, 2021). "CD47 showed the next highest expression among cancer cell lines, while the remaining antigens had relatively similar levels of expression, with the exception of EPCAM having a considerable level of expression in Panc02." (PMID 33690223, 2021). "Blockade of CD47-SIRPα signaling is a strategy to promote macrophage phagocytosis of many cancer cells, which is discussed in the therapeutic section." (PMID 33763066, 2021). "CD47, a cell surface protein which is overexpressed on most cancer cells, is an important “don’t eat me” signal." (PMID 35111663, 2021). "Preclinical data on anti-CD47 cancer therapy is promising, and clinical trials have shown optimistic results in ameliorating tumor growth." (PMID 33977286, 2021). "Cancer cells express CD47 in significant amounts, resulting in Sirpa activation and inhibition of macrophage-mediated destruction." (PMID 34204832, 2021). "Recent advances provide evidence that the cellular signalling pathway comprising the ligand-receptor duo of thrombospondin-1 (TSP1) and CD47 is involved in mediating a range of diseases affecting renal, vascular, and metabolic function, as well as cancer." (PMID 33920030, 2021). "CD47 is an anti-phagocytic molecule that was found to be constitutively expressed in certain myeloid leukemias, indicating its role in assisting cancer cells by evading phagocytic recognition." (PMID 33977286, 2021). "CD47 interacts with the signal-regulatory protein alpha (SIRPα) on the surface of phagocytic cells, weakening the ability of macrophages to engulf cancer cells." (PMID 34503245, 2021). "A promising approach in cancer immuno-therapy consists of blocking CD47-SIRPα interaction, and its therapeutic potential (as a monotherapy or in combination) is currently under investigation in multiple clinical trials." (PMID 34471125, 2021). "CD47 on cancer cells interacts with signal regulatory protein alpha (SIRPa) on macrophages/microglia to signal a block in their phagocytosis." (PMID 33214223, 2021).